Y_RNA (Y RNA )
Gene: Miscellaneous RNA gene on chromosome 20 (34,526,510 to 34,526,606, reverse strand). Ensembl gene ENSG00000206582.
Homologues: Orthologues: chimpanzee Y_RNA (100% identical), macaque Y_RNA (98% identical). Paralogues in human: Y_RNA (93% identical), RNY3 (91% identical), Y_RNA (91% identical), RNY3P1 (90% identical), Y_RNA (90% identical), Y_RNA (89% identical), Y_RNA (88% identical), RNY3P11 (87% identical), Y_RNA (87% identical), RNY3P14 (86% identical), RNY3P5 (86% identical), Y_RNA (86% identical), and 96 more.